MIF (macrophage migration inhibitory factor)
Diseases named in the same sentence as MIF in open-access papers (continued):
Sharing a sentence is not in itself a finding about the gene and the disease.
cancer (continued). "Theoretically, immunotherapeutic vaccines have merit over chemical inhibitors or anti-MIF antibodies since the former can also lead to a cell-mediated immune response against MIF-producing cancer cells in addition to a humoral immune response against MIF capable of neutralizing MIF activity." (PMID 34389619, 2021). "MIF is now known to have a pivotal role in metabolic, acute inflammatory, autoimmune and infectious diseases, and cancers including colorectal, malignant melanoma, lung, breast, and prostate cancers as well as glioblastomas." (PMID 33776775, 2021). "Collectively, these results suggested that CD8+ T cells cocultured with DCs infected with rSmeg-hMIF-hIL-7 could exert the strongest CTL response against cancer cells, resulting in reduced MIF secretion from cancer cells." (PMID 34389619, 2021). "MIF is involved in the progression, invasion, and proliferation of many cancers." (PMID 34407796, 2021). "Since MIF has various biological functions, including inflammation induction or cancer promotion, direct MIF protein challenge as a vaccine component could have a risk of generating unwanted biological phenotypes." (PMID 34389619, 2021). "Collectively, this study uncovers that MIF surveils DNA replication fidelity in cancer cells and identifies a hitherto unknown intrinsic mechanism to help cancer cells evade DNA replication stress for their survival." (PMID 34012010, 2021). "Taken as a whole, current and previous results seem to indicate that MIF molecule might be an important checkpoint inducing transformation into an aggressive and metastatic form of cancer." (PMID 34157052, 2021). "Our oncogenic studies clearly showed that MIF promotes cancer cell growth in vitro and in vivo through its nuclease activity, which provide the functional evidence that MIF’s proofreading function helps cancer cells cope with DNA replication stress for their survival." (PMID 34012010, 2021). "Early phase clinical trials are evaluating anti-MIF therapies for cancer treatment." (PMID 32155795, 2020). "In addition, evidence generated during the last 15 years has also supported a pro-oncogenic role of MIF in certain types of cancers." (PMID 32155795, 2020). "In addition to cancer cells, MIF is upregulated in myeloid and lymphocyte lineage cell types in response to various activating ligands as well as DAMPs, PAMPs, and environmental metabolic changes." (PMID 33324425, 2020). "Importantly, the expression of MIF is directly and positively correlated with the aggressiveness of the cancer phenotype." (PMID 32317702, 2020). "Finally, MIF has been proposed as a tumorigenic factor, with upregulation seen in various cancers and increased MIF expression found to correlate with worse prognosis." (PMID 32244916, 2020). "However, the relationship between the inflammatory, chemotactic, and proliferative capacities of MIF and cancer severity is still unclear." (PMID 32481584, 2020). "Overexpressed MIF levels in multiple models of cancer have been reported." (PMID 32481584, 2020). "Moreover, CXCR4 is a major receptor driving cancer metastasis, and not only the CXCR4/CXCL12 but also the CXCR4/MIF axis has been implicated in this process." (PMID 33239628, 2020). "The genetic inhibition of autophagy also increased MIF secretion to the culture media in the 66cl4 cell line, indicating that blocking the autophagic process in cancer cells induced the secretion of MIF and that the effect was not limited to pharmacological or lysosomal inhibition of autophagy." (PMID 31963754, 2020). "MIF overexpression has been reported in several cancer types, including GBM." (PMID 30814573, 2019). "In addition, an anti-MIF mAb has been tested in Phase II trials in patients with cancer (NCT02448810, NCT02540356)." (PMID 31752120, 2019). "Conversely, MIF protects HIF-1α from proteasomal degradation in cancer cells." (PMID 30634708, 2019).
cancer (continued). "The production of lactate and MIF by cancer cells infected with HPV could partly explain why such cells are poorly immunogenic." (PMID 30634708, 2019). "Furthermore, nine cancer biomarkers: MIF, TNFα, sFasL, TRAIL, FGF2, SCF, prolactin and OPN, were negatively correlated to Lactobacillus abundance and positively correlated to levels of vaginal pH." (PMID 31089160, 2019). "MIF is a novel client of HSP90 in cancer cells, and this prevents its degradation." (PMID 29707160, 2018). "Some studies also found that inhibiting the function of MIF could significantly reduce the growth of cancer in vitro or in vivo systems, such as bladder cancer, lung cancer, and colon cancer." (PMID 30386232, 2018). "Moreover, MIF is an immunomodulatory protein that attenuates immune activation and participates in the immune escape of diverse types of malignant tumors." (PMID 29896883, 2018). "The application of anti-MIF monoclonal antibodies in cancer has only recently been explored." (PMID 29707160, 2018). "The large body of data accumulated on the role of MIF in oncogenesis suggests that MIF may represent a therapeutic target in several cancers including GBM." (PMID 29707160, 2018). "We hypothesized that loss of MIF expression in the 4T1 cancer cells would promote ICD, which could explain the enhanced immune response observed in the MIF KD tumors." (PMID 29864117, 2018). "MIF has important roles in the TME as well as progression of many cancers." (PMID 28957348, 2017). "Accordingly, MIF blood levels are increased in patients with arthritis, systemic lupus erythematosus, psoriasis, atopic dermatitis, ulcerative colitis, asthma, and cancer." (PMID 28179905, 2017). "How MIF secretion is regulated in cancer is unknown, and targeting MIF at the level of secretion could have therapeutic significance." (PMID 26741693, 2016). "Serum levels of MIF in cancer have become of significant interest in the clinical setting." (PMID 26741693, 2016). "Previous studies described the elevation of MIF in the circulation of cancer patients." (PMID 27636991, 2016). "In the current paper, we have discovered novel stimuli of MIF secretion in cancer that could have clinical implications." (PMID 26741693, 2016). "MIF is a pro-inflammatory cytokine overexpressed in various cancers." (PMID 26883190, 2016). "Via CXCR4, MIF has been shown to recruit many cell types, including T-cells, B-cells, eosinophils, endothelial progenitor cells, mesenchymal stromal cells, as well as cancer cells." (PMID 26347749, 2015). "We suggest that targeted MIF therapy might be effectively combined with antibody-based therapy to improve patient outcome in other cancers including GBC." (PMID 26530123, 2015). "Therefore, this study provides new insights into the biological function of MIF as an autophagy modulator in cancer therapy." (PMID 26633714, 2015). "Group A included the samples that expressed MIF in the primary cancer tissues at levels less than in the liver metastases, while Group B included the samples that expressed MIF in primary cancer tissues at levels greater than or equal to that of the liver metastases." (PMID 26087187, 2015). "MIF is a direct target of HIF1α and is described as a link between inflammation and cancer, contributing to a microenvironment favouring cancer progression." (PMID 26183215, 2015). "Overexpression of MIF has been reported in multiple human cancers." (PMID 26530123, 2015). "Although additional functional studies are required, our results suggest that suppression of MIF by RNA interference may be a potentially important therapeutic modality for MIF-positive cancers." (PMID 25015194, 2014). "Therefore, we can propose that repetitive, daily dosing of ISO-66 effectively reduces the cancer-promoting effects of MIF." (PMID 25050663, 2014). "An increase of MIF levels positively correlates with a poor prognosis in cancer." (PMID 25050663, 2014). "Many MIF-inactivating strategies have proven successful in delaying cancer growth." (PMID 25050663, 2014).
cancer (continued). "Similarly, several panHDAC inhibitors reduced the production of the tumorigenic cytokine macrophage migration inhibitory factor (MIF) in several human cancer cell lines as well as in mouse blood." (PMID 25115382, 2014). "Studies of MIF function and expression in cancer have revealed a largely pro-tumorogenic role." (PMID 25328446, 2014). "However, following its cloning and the biochemical characterization and preparation of MIF protein, MIF was later on redefined to be a pleiotropic inflammatory cytokine with critical roles in physiological immunity but also inflammatory diseases and cancer." (PMID 23720662, 2013). "Macrophage migration inhibitory factor (MIF) is important in regulating cell proliferation and apoptosis in both normal and cancerous cells, and may be important in cancer progression and metastasis." (PMID 23522304, 2013). "Moreover, gene silencing of MIF or SCD1 has been carried out for many kinds of cancers, again with the exception of STS." (PMID 24167613, 2013). "Consequently autophagy induced by MIF facilitates the development of cancer resistance to chemotherapy-induced cell death." (PMID 22629429, 2012). "MIF is involved in the pathogenesis of many inflammatory diseases and cancer development." (PMID 21283538, 2011). "Therefore, strong evidence has accumulated suggesting that MIF is an important link between inflammation and cancer." (PMID 22168770, 2011). "Consequently, MIF is a central modulator of inflammation and a possible link between chronic inflammation and cancer." (PMID 22168770, 2011). "In our prospective, descriptive study we assessed the induction of macrophage migration inhibitory factor levels in cancer patients undergoing bowel resection (elective enterotomy) in comparison with cancer patients undergoing liver resection (without enterotomy)." (PMID 21091281, 2011). "MIF has been identified as a hypoxia-induced gene in cancer cells." (PMID 20727156, 2010). "Moreover, studies about co culture of macrophages with cancer cell lines showed that MIF expression is induced in a JNKII and NF-kB-dependent manner and acts inducing macrophages MMP release, promoting tumoral cells invasively." (PMID 19949545, 2009). "MIF represents an important link between inflammation and cancer." (PMID 18493321, 2008). "CenpA, dad1, BI-1 and MIF are also overexpressed in human cancers." (PMID 17311107, 2007). "Furthermore, it is conceivable that a better understanding of MIF biology will help to design novel strategies for cancer treatment." (PMID 17640378, 2007). "The present study is the first report to document MIF mRNA expression in prostate epithelial cells and to reveal altered MIF expression in cancer using the complementary techniques of in situ hybridization and immunostaining within matched samples from the same patient." (PMID 16000172, 2005). "Thus, our data show that CaP patients have a significantly higher MIF serum level (5.87 ± 3.91 ng/ml, n = 115) when compared to non-cancer patients (2.19 ± 2.65 ng/ml, n = 158) and this difference is statistically significant (p < 0.0001)." (PMID 16000172, 2005). "MIF protein was localized predominantly within the epithelium in both benign prostate and cancer." (PMID 16000172, 2005). "Furthermore, MIF inhibition in MASLD led to a reduction in integrinβ+CD44+ cancer cells." (PMID 41545340, 2026). "In addition, it should be noted that elevated MIF levels or association with diseases including virus-associated cancer do not necessarily imply direct functional interactions or causality, which definitely require more experimental evidence." (PMID 41472252, 2025).
cancer (continued). "The pharmacological targeting of MIF signaling pathways and receptors using small synthetic molecules (nanobodies), antibodies, or receptor-targeted peptides, is of particular interest in cancer treatment, as it counteracts the pro-proliferative effects of MIF and D-DT." (PMID 40426915, 2025). "Moreover, MIF has profound and detrimental effects on anti-cancer immune responses." (PMID 38178143, 2024). "They suggested that MIF inhibitor could be used in the combination therapy for cancer." (PMID 38629624, 2024). "In addition to being an initiator of inflammation, MIF is also reported as a major immunosuppressive factor, although this may be restricted to certain contexts such as cancer." (PMID 36672343, 2023). "Therefore, we speculate that pathologic properties of MIF can be attributed to oxMIF, which reflects a druggable isoform of MIF in cancer." (PMID 37067909, 2023). "Additionally, MIF could promote cancer growth, invasion, and angiogenesis in several types of tumors, highlighting MIF as a prognostic biomarker." (PMID 35203511, 2022). "In addition, knockout and inhibitors of MIF suppressed cancer cell growth." (PMID 35091838, 2022). "Of the 11 cytokines that showed evidence of a causal link with a cancer, records on past or present clinical drug development programmes were identified for six cytokines (RANTES, MIF, VEGF, IL-1ra, MIP1a, sICAM), four of which on drugs that have already been marketed (MIF, VEGF, IL-1ra and sICAM)." (PMID 35012533, 2022). "In addition, select immune mediators and cancer biomarkers also exhibited high importance scores in our analyses for predictions of LD and vaginal pH (MIF), as well as genital inflammation (IL-6, IL-10, MIP-1α), further confirming the link between vaginal microbiota and host immune responses." (PMID 35196323, 2022). "In addition to the ability of MIF to counteracting glucocorticoid-induced anti-inflammatory responses, and its key role in the inflammatory cascade, MIF also participates in regulating the malignant phenotypes of various cancers by activating multiple signaling pathways." (PMID 36042480, 2022). "Furthermore, MIF is secreted by ionizing radiation and other DNA-damaging stresses in cancer cells." (PMID 34516577, 2021). "In T cell-mediated anticancer effect, rSmeg-hMIF-hIL7 may have merit over ibudilast in that the former can lead to vaccine-mediated activation of T lymphocytes capable of killing MIF-producing cancer cells as well as recovery of T cell function mediated by MDSC inhibition." (PMID 34389619, 2021). "Indeed, we found that rSmeg-hMIF-hIL-7 elicited an enhanced CTL response against CD4+ and CD8+ T cells cocultured with infected dendritic cells compared with rSmeg expressing h-MIF alone or h-IL-7 alone, suggesting an adjuvant effect of IL-7 in cancer immunotherapy." (PMID 34389619, 2021). "Since the anti-MIF IgG level in mouse serum was increased in response to rSmeg-hMIF-hIL-7, the serum of vaccinated mice may neutralize MIF and regulate the malignant character of cancer cells." (PMID 34389619, 2021). "Therefore, efforts to inhibit MIF signaling in cancer should target DDT together." (PMID 34516577, 2021). "Moreover, MIF was shown to be up-regulated under hypoxia in endothelial and cancer cell lines." (PMID 34366876, 2021). "We introduced a recombinant Mycobacterium smegmatis (rSmeg-hMIF-hIL-7) vaccine that could deliver a fusion protein of human macrophage migration inhibitory factor (MIF) and interleukin 7, which could act as a target antigen and as an adjuvant of cancer vaccine, respectively." (PMID 34389619, 2021). "Thus, MIF’s nuclease activity is a therapeutic vulnerability in cancers." (PMID 34012010, 2021). "In a study of PC induced liver premetastatic niche formation, the upregulation of the macrophage migration inhibitory factor (MIF) was found to be an early event of cancer progression that could be detected from plasma exosomes of stage I PC patients who later developed liver metastasis." (PMID 33297544, 2020).
cancer (continued). "Similarly, previous studies demonstrated that MIF was induced by hypoxia in cancer cells." (PMID 31866994, 2019). "Indeed, as MIF is a client of Hsp90 and is highly stabilized in many cancers, Hsp90 inhibitors could be a treatment of choice to reduce MIF levels." (PMID 31013837, 2019). "Indeed, in many cancer types, MIF has been shown to be highly stabilized by Hsp90." (PMID 31013837, 2019). "Besides its role in inflammation, MIF has potent proangiogenic properties and in conjunction with its cell surface receptor CD74 emerges as an important regulator of pathological angiogenesis associated with several types of malignant tumors." (PMID 31866994, 2019). "Notably, these cancer biomarkers functionally comprised of several cytokines (IL-6, MIF, TGF-α, TNFα), apoptosis-related proteins (sFas, sFasL, TRAIL), growth and angiogenic factors (FGF2, HGF, SCF, VEGF), hormones (leptin, prolactin) and other biomarkers (AFP, OPN), but not carcinoma antigens." (PMID 31089160, 2019). "Furthermore, anti-MIF antibodies suppressed angiogenesis in animal models of cancer." (PMID 31866994, 2019). "Combination of a potent MIF inhibitor with any of the promising immunotherapy options already in the clinic, or those in the developmental pipeline could lead to robust, long-lasting immunity in the setting of cancer." (PMID 29864117, 2018). "Indeed, the restriction of MIF showed the efficacy of cancer treatment." (PMID 27788497, 2017). "Increased paracrine release of the pro-inflammatory cytokine macrophage migration inhibitory factor (MIF) during NE differentiation in PC may facilitate cancer progression or recurrence, especially following androgen deprivation, through stimulation of AKT and ERK1/2 signaling pathways." (PMID 25699233, 2015). "MIF demonstrates an immune modulatory function; thus, recombinant mycobacteria producing MIF might be effectively used for several immunotherapeutic purposes, such as anti-cancer therapy or potentiating vaccines." (PMID 25822634, 2015). "In addition to auto- and paracrine effects on cancer cells, MIF could contribute to shape the microenvironment leading to immunomodulation and angiogenesis, these aspects deserving further investigations." (PMID 24939415, 2014). "Given the known functions of MIF in pro-inflammatory pathways, and the weight of evidence associating inflammatory pathways and the development of cancer, it comes as no surprise that MIF is emerging as a key player in the progression and growth of many tumors." (PMID 23522304, 2013). "In addition, MIF displays a dominant role in diseases that are characterized by pro-inflammatory pathways, such as the severity of rheumatoid arthritis, cardiac dysfunction that is seen in sepsis, Crohn’s disease, and many different cancers." (PMID 23522304, 2013). "Moreover, MIF has been identified as a hypoxia-induced gene in cancer cells." (PMID 18493321, 2008). "MIF may also mediate some of the stimulatory effects of inflammation on cancer progression." (PMID 18060075, 2007). "However, at least three genes induced in the fibroblast serum response, PLAUR, LOXL2, and MIF, have been previously shown to increase cancer invasiveness or angiogenesis in animal xenograft models; each of these three genes has also been shown to play an important role in wound healing." (PMID 14737219, 2004). "Dual inhibition of MIF and its homolog DDT has been proposed as a novel therapeutic strategy to overcome immune checkpoint inhibitor resistance in different types of cancer." (PMID 41597203, 2026). "Specifically, ligand–receptor pairs, such as MIF (CD74–CXCR4) and MIF (CD74–CD44), indicate the importance of CD44 in epithelia, cell proliferation, and certain cancers." (PMID 40605976, 2025). "Blocking CD74 has been shown to inhibit MDA-MB-231 cell proliferation, highlighting the role of MIF/CD74 signaling in driving the growth of both non-invasive and invasive cancer cells." (PMID 41159021, 2025).